TMEM266 (transmembrane protein 266)
Description:
Voltage-sensor protein present on the post-synaptic side of glutamatergic mossy fibers and granule cells in the cerebellum. Despite the presence of a voltage-sensor segment, does not form a functional ion channel and its precise role remains unclear. Undergoes both rapid and slow structural rearrangements in response to changes in voltage. Contains a zinc-binding site that can regulate the slow conformational transition.
Synonyms: hTMEM266; HsHVRP1; C15orf27; HVRP1; FLJ38190
Gene: Protein-coding gene on chromosome 15 (76,059,936 to 76,229,121, forward strand). Ensembl gene ENSG00000169758.
Subcellular location: Cell membrane; Cell projection, dendrite; Perikaryon
Subcellular location (Human Protein Atlas): Cytosol; Plasma membrane
Gene Ontology:
Molecular function: channel activity; protein binding; protein homodimerization activity; voltage-gated channel activity
Biological process: monoatomic ion transport; transmembrane transport
Cellular component: cytosol; dendrite; perikaryon; plasma membrane; membrane
Genetic constraint (gnomAD): Loss-of-function variants: 35 observed, 50.34 expected, observed/expected ratio (o/e) 0.7, 90% interval 0.53 to 0.92. The upper end of that interval is the gene's LOEUF score, 0.92, which puts it in group 3 of 6, group 1 being the genes least tolerant of losing a copy. Missense variants: 655 observed, 692.8 expected, observed/expected ratio (o/e) 0.95, 90% interval 0.89 to 1.01. Synonymous variants: 310 observed, 287.06 expected, observed/expected ratio (o/e) 1.08, 90% interval 0.98 to 1.19.
Homologues: Orthologues: chimpanzee TMEM266 (99% identical), macaque TMEM266 (97% identical), pig TMEM266 (93% identical), mouse Tmem266 (89% identical), rat Tmem266 (88% identical), rabbit TMEM266 (88% identical), guinea pig TMEM266 (86% identical), zebrafish tmem266 (62% identical), dog TMEM266 (40% identical), tropical clawed frog TMEM266 (34% identical). Paralogues in human: TNS1 (20% identical), TNS3 (20% identical), TPTE2 (8% identical), HVCN1 (7% identical), TPTE (7% identical), PTEN (6% identical).
Diseases named in the same sentence as TMEM266 in open-access papers:
TMEM266 is named in the same sentence as 3 diseases in open-access papers, as found by Europe PMC text mining. Sharing a sentence is not in itself a finding about the gene and the disease. The quoted sentences say what the papers report.
tumor (1 paper, 2022). "COL4A1, COL6A3, FAP, and LY6E were up-regulated in the tumor group in the training set, whereas ABCA8, MAMDC2, TMEM100, and TMEM266 were down-regulated." (PMID 36685898, 2022).
TMEM266 also shares sentences with these, for which no sentence is quoted: breast carcinoma (1 paper); rheumatic disease (1).